FTO (FTO alpha-ketoglutarate dependent dioxygenase)
Diseases named in the same sentence as FTO in open-access papers (continued):
Sharing a sentence is not in itself a finding about the gene and the disease.
Obesity (continued). "Most researchers focus on the reducing obesity risk caused by FTO gene polymorphisms under exercise, while there are few on its function." (PMID 36163017, 2022). "Other two FTO gene variants, the rs8050136 and the rs1421085, were found associated to obesity traits in different children population studies alone or in combination to the best investigated rs9939609 variant." (PMID 36452324, 2022). "As an additional link between epitranscriptomics and hypertension, an SNP-variant of FTO has been associated with obesity and elevated systolic blood pressure." (PMID 35991314, 2022). "An Asian population study used MR analysis to identify causal associations between fat mass, the obesity-associated gene (FTO) and various types of senile cataracts." (PMID 36572895, 2022). "Eighteen FTO SNPs were associated with significant increased obesity risk and interacted with physical activity (p < 0.001), wine consumption (p < 0.014) and SSB consumption (p < 0.01)." (PMID 36235854, 2022). "Genome-wide associated studies (GWAS) showed that genetic variants of the FTO gene were associated with obesity in multiple populations." (PMID 36461116, 2022). "On the other hand, the demethylation activity (i.e., the removal of the methyl group from m6A) is mainly controlled by two independent demethylases: fat mass and obesity-associated (FTO) and AlkB homolog 5, RNA demethylase (ALKBH5)." (PMID 35892568, 2022). "FTO was the first obesity-susceptibility gene discovered through GWAS in European patients with type 2 diabetes." (PMID 36232301, 2022). "Human 2OGDD acting on nucleic acids, are alkylation repair enzyme homologs (ALKBH 1‐8), the TETs, and the fat mass and obesity‐associated (FTO) protein." (PMID 35852137, 2022). "Claussnitzer group studied the mechanism of FTO variant (T-to-C) rs1421085, in connection with obesity; as it was shown to disrupt a conserved repressor motif (ARID5B)." (PMID 35409166, 2022). "The fat mass and obesity-associated (FTO) gene is a key allele of obesity moderating satiety responsiveness, food intake, and binge eating, and the variational expressions in FTO lead to obesity." (PMID 35013513, 2022). "We found a significant association of eighteen common FTO obesity-predisposition SNPs with the risk of obesity in the Israeli population." (PMID 36235854, 2022). "Using a large, cross-sectional, multiethnic population from several distinct cohorts, one research group identified a protective effect of the obesity risk fat mass and obesity-associated (FTO) rs9939609 on depression." (PMID 35308733, 2022). "In humans, the FTO SNP rs9939609 was found to be linked to body mass index and is believed to be one of the strongest genetic determinants of obesity propensity." (PMID 35350378, 2022). "Genome-wide association studies (GWAS) identified single-nucleotide polymorphisms (SNPs) within FTO to be associated with obesity, as well as cancer including endometrial cancer, breast cancer, pancreatic cancer, and melanoma." (PMID 35409166, 2022). "FTO overexpression in mice increases fat mass, whereas its deficiency protects mice against obesity, implying a key role of FTO in obesity." (PMID 35282837, 2022). "Variants in the fat mass and obesity-associated (FTO) gene (rs1558902, rs1121980, rs9939609, and rs9941349) showed a robust yet ethnicity-independent link with obesity." (PMID 36362270, 2022). "This modification can also be reverted, and the FTO protein (fat mass and obesity-associated gene) has been identified as the first m6a eraser with a recognized role as a genetic factor for obesity." (PMID 35184223, 2022). "Epidemiological studies reported strong associations of FTO SNPs with obesity, as well as various cancers." (PMID 35409166, 2022). "Pharmacological inhibition of the fat mass and obesity-associated FTO protein is emerging as a promising strategy to develop a therapeutic treatment for obesity and cancer, and several inhibitors of the enzyme have been described in the literature." (PMID 35398093, 2022).
Obesity (continued). "The fat mass and obesity-associated (FTO) gene is one of the genetic factors known to contribute to polygenic obesity (obesity caused by a combination of genetic variants) and is involved in body weight and adiposity regulation." (PMID 35800074, 2022). "Specifically, the secreted SPP1 and the nuclear PPARγ and FTO were included among the down modulated genes associated to severe obesity pathway after PBMCs treatment with EVOO, while ADIPOQ was up regulated." (PMID 36386923, 2022). "In fact, common FTO gene polymorphisms have the largest effect known on BMI and obesity risk across ancestries, among adults, children and adolescents." (PMID 36235854, 2022). "Genomically, intron 1 and 2 of the FTO gene show the strongest genome- association with obesity, where 89 variants were identified." (PMID 35409166, 2022). "Fat mass and obesity-associated (FTO) and alkB homologue 5 (ALKBH5) have been identified as demethylase, which promote the dumping of a methyl group from m6A via different mechanisms." (PMID 35821163, 2022). "In one example, utilizing genome-wide association studies (GWAS), the fat mass and obesity associated (FTO) gene was discovered in 2007 as the first gene associated with an increase in body mass index." (PMID 37990728, 2022). "FTO was the most important gene involved in obesity, which was also implicated in the regulation of adipocyte thermogenesis." (PMID 36499740, 2022). "This mice study also found that Irx3 is a functional long-range target of obesity-associated variants within the FTO gene, and both Irx3 and FTO interact, increasing body fat deposition and leading to obesity among animals." (PMID 35498742, 2022). "FTO is a recently discovered gene associated with obesity, but there is already evidence that FTO plays a role in these psychiatric disorders." (PMID 35528183, 2022). "FTO is a recognised genetic risk factor for the development of obesity, and the FTO protein it encodes belongs to a group of mRNA-demethylating enzymes at the m6A (N6-adenosine-modified) and m6Am (N6,2’-O-dimethyladenosine-modified) sites." (PMID 36232910, 2022). "FTO was originally thought to be a regulator of body weight and obesity because FTO deficiency leads to growth retardation, while FTO overactivation increases food intake and contributes to obesity." (PMID 35064107, 2022). "Using lentiviral-mediated stable gene knockdown in SGBS cells, we found that fat mass and obesity associated (FTO), the major obesity gene, inhibits adipocyte browning." (PMID 35986215, 2022). "Researchers have identified more than 1,000 possible obesity-related loci after the publication of the first obesity-related genome-wide association study (GWAS) in 2007, which demonstrated BMI-associated single-nucleotide polymorphisms (SNPs) in the FTO gene." (PMID 36536439, 2022). "Since obesity was an accepted risk factor for some common diseases, it was reasonable to assume that FTO was a factor contributing to Human Diseases." (PMID 35628623, 2022). "Demethylases including fat mass and obesity associated (FTO) and ALKHB5 catalyze the m6A demethylation." (PMID 35311620, 2022). "Nevertheless, translating the findings from such studies to molecular roles of FTO variants in obesity is a continuous challenge." (PMID 35409166, 2022). "The purpose of this study was to investigate the effect of fat mass and obesity-associated (FTO) rs9939609 polymorphism on the association between colorectal cancer and dietary fiber." (PMID 36263301, 2022). "Expression patterns and clinical significance of fat mass and obesity-associated protein (FTO) were determined through bioinformatics analysis, real-time PCR, western blotting, immunohistochemistry." (PMID 36263177, 2022). "Further investigating actionable interactions between lifestyle factor and FTO polymorphisms, we studied the interaction between wine consumption and FTO rs9939609 variation on obesity risk." (PMID 36235854, 2022).
Obesity (continued). "Significant gene–environmental interaction was found for the rs9939609 FTO, where physical activity significantly reduces the FTO genetic obesity predisposition." (PMID 36235854, 2022). "The FTO gene encodes proteins participating in both adipogenesis and tumorigenesis, and is thus another link regarding obesity and cancer." (PMID 37990728, 2022). "The first GWAS for obesity traits identified a cluster of common variants in the first intron of the fat mass and obesity-associated (FTO) locus that was convincingly associated with BMI." (PMID 36360211, 2022). "We addressed the regulation of m6A and its demethylase fat mass and obesity-associated (FTO) after MI and their association with HF." (PMID 35892568, 2022). "The same MC4R variant (rs17782313) and an FTO variant (rs9930506) were significantly associated with obesity in children, reported in multiple separate studies involving thousands of individual subjects, particularly Caucasians and Asians." (PMID 36232301, 2022). "In the Brazilian admixed population, the FTO polymorphisms were associated with the development of obesity in adults and in children and youth, probably due to the high percentage of European ancestry in the studied samples." (PMID 35560161, 2022). "The study aims to explore the potential role and the regulatory mechanism of fat mass and obesity associated (FTO) in osteosarcoma (OS) progression." (PMID 35311620, 2022). "Mechanistically, senescent neutrophils-derived exosomal piRNA-17560 enhances the expression of fat mass and obesity-associated protein (FTO) in breast cancer cells." (PMID 36302751, 2022). "A large cohort study of Korean populations has also shown that FTO SNP rs9939609 is significantly associated with body mass index (BMI), a common measure of obesity." (PMID 35999587, 2022). "FTO is an obesity susceptibility gene and encodes 2-oxoglutarate and Fe (II)-dependent demethylase catalyzing the 3-methylthymine in single-stranded DNA and 3-methyluracil and 6-methyladenosine in RNA for repairing and modifying multiple nucleic acids." (PMID 36105080, 2022). "The FTO gene, known to be the first genome-wide association study (GWAS)-identified obesity gene, has previously been shown to have a relationship with obesity and metabolic pathways in European children and adults." (PMID 35327974, 2022). "The fat mass and obesity-associated FTO protein catalyzes demethylation of the N6-methyladenosine, an epigenetic mark that controls several metabolic pathways by modulating the transcription, translation, and cellular localization of RNA molecules." (PMID 35398093, 2022). "Fetal genes that had significant interactions with maternal smoking during pregnancy were glutathione S-transferase theta 1 (GSTT1) and fat mass and obesity-associated protein (FTO)." (PMID 35675978, 2022). "The FTO was identified for the first time in Europeans in 2007, and shortly thereafter, its association with BMI and obesity risk was confirmed by three other studies." (PMID 34990463, 2022). "The fat mass and obesity-associated (FTO) gene encodes for the alpha-ketoglutarate-dependent dioxygenase." (PMID 36362270, 2022). "A total of 21 potential obesity-associated variants, other than FTO, were subsequently surveyed, and six of them were found to be significantly associated with BMI (1.47 × 10-14 ≤ P ≤ 0.04)." (PMID 35308733, 2022). "FTO was initially described as a gene linked to obesity and energy homeostasis and was then recognized as the nucleic acid demethylase." (PMID 36302751, 2022). "FTO gene is also one of the most associated with obesity which has been identified as a risk gene for addiction." (PMID 35528183, 2022). "The first genome-wide association study (GWAS) identified associations of the obesity-susceptibility locus, FTO, with a 0.39-kg/m2 unit increase in BMI per risk allele." (PMID 35016652, 2022).
Obesity (continued). "Although obesity is a common risk factor for GDM, fat-mass/obesity-associated gene variants that predispose to T2D (e.g., FTO) have been linked to GDM in candidate gene studies but not yet in GWAS." (PMID 36432486, 2022). "FTO is responsible for controlling fatty acid transport, adipogenesis, fat metabolism, and obesity susceptibility." (PMID 36035182, 2022). "In this study, the decreased m6A level was first detected and high expression of fat mass and obesity-associated protein (FTO) was responsible for the m6A suppression in NPM1-mutated AML." (PMID 35211409, 2022). "Often FTO variants have been investigated with variants in the MC4R of which mutations can be positioned between monogenic obesity and the polygenic obesity." (PMID 36452324, 2022). "We investigated obesity-related polymorphisms in the FTO gene (rs9939609, rs17817449) and ADRB2 (rs1042713, rs1042714) as candidate risk factors concerning excessive GWG in pregnant women with pregestational diabetes." (PMID 35268025, 2022). "The FTO gene rs9939609 polymorphisms was significantly associated with obesity in different populations, including Chinese population." (PMID 36619747, 2022). "They provided evidence that rs10767664 and rs3751812 SNPs in the BDNF and fat mass are associated with obesity and obesity-associated (FTO) genes, respectively." (PMID 36676721, 2022). "We investigated the interaction of common FTO SNPs with actionable environmental factors, namely physical activity, sugar-sweetened beverages (SSB) and wine consumption, and verified FTO common SNPs predisposition to obesity in the Israeli population." (PMID 36235854, 2022). "In humans, mutations in FTO lead to a significant increase in body mass index, obesity, and a predisposition to diabetes." (PMID 35682599, 2022). "After adjusting for potential confounders (age and gender), inactive individuals FTO rs9939609 risk-allele carriers (TA and AA) demonstrated higher obesity risk compared to their physically active counterparts (β = 1.048, p < 0.001)." (PMID 36235854, 2022). "Genome-wide association studies have identified associations of SNPs in the first intron of FTO with BMI and obesity that have been replicated in different populations and age groups." (PMID 36126070, 2022). "After LPS injection, m6A methylation is increased in mouse myocardial tissues, while the expression of fat mass and obesity-associated protein (FTO, an m6A demethylase) is decreased correspondingly." (PMID 36505499, 2022). "The fat mass and obesity associated (FTO) gene, located on chromosome 16, was identified through mutant mouse studies." (PMID 36235854, 2022). "Since SNPs can impair function rather than complete loss of function (as performed in mice knockout studies); there is a need for more accurate models that reflect human FTO variants and their consequences in adipogenesis and obesity." (PMID 35409166, 2022). "It is reported that mutations in the FTO gene raise blood levels of leptin, a known mediator or growth factor between obesity and colon cancer, which activates a variety of pathways associated with colon cancer." (PMID 36292657, 2022). "Herein, we focused on four ORGs: fat mass and obesity-associated (FTO), melanocortin-4 receptor (MC4R), glucosamine-6-phosphate deaminase 2 (GNPDA2), and transmembrane protein 18 (TMEM18)." (PMID 36289871, 2022). "Instead, an association between a higher risk of PC in Japanese people and the FTO gene was found, presumably through a mechanism unrelated to obesity." (PMID 35959181, 2022). "In this regard, FTO is one of the most representative obesity-related genes, which has been widely studied due to its association with multiple obesity phenotypes and diabetes." (PMID 35948824, 2022). "The epigenetic effects of the FTO gene, a key genetic predictor of obesity and CVD risk factor, stand out among other potential genes." (PMID 36551003, 2022).
Obesity (continued). "In contrast, METTL15, zinc finger CCCH-type containing 13 (ZC3H13), fat mass and obesity-associated (FTO), leucine-rich pentatricopeptide repeat containing (LRPPRC), and RNA-binding motif protein 15B (RBM15B) showed widespread CNV frequency loss." (PMID 34979500, 2022). "The SNP with the most significant association with obesity among numerous populations is FTO Alpha-Ketoglutarate Dependent Dioxygenase (FTO)." (PMID 36278751, 2022). "We provide recent findings confirming FTO’s causative link to obesity and discuss novel approaches using RNA demethylase inhibitors as targeted oncotherapies." (PMID 35409166, 2022). "The fat mass and obesity-associated (FTO) gene is a well-known prominent factor in predicting obesity and is the first m6A eraser to be discovered in eukaryotic cells." (PMID 36035182, 2022). "Instead, we limited our investigation to MR studies that use SNPs in the fat mass and obesity-associated (FTO) gene as IV to investigate the causal effect of adiposity on diverse outcomes." (PMID 35186031, 2022). "We demonstrate that FTO common obesity SNPs interact with actionable environmental factors and are associated with obesity in the Israeli population." (PMID 36235854, 2022). "Innovatory research was performed by Yu (2021), involving human FTO – an enzyme mediating RNA m6A demethylation and originally identified as a fat mass- and obesity-associated protein – which was introduced to the genomes of rice and potato." (PMID 36684776, 2022). "Two journals about obesity primarily include FTO as a research target, and to a lesser extent, 5 other genes linked to obesity." (PMID 34990452, 2022). "FTO, being first identified as a susceptibility gene for obesity and T2D, can remove m6A methylation from RNA in the nuclear speckles, whereas ALKBH5 specifically demethylates m6A-methylated RNAs in the nucleus." (PMID 35053407, 2022). "We found that the total m6A methylation level was significantly increased, and the expression of fat mass and obesity-associated protein (FTO) was downregulated after CIRI." (PMID 36479246, 2022). "Studies reported that the expression level of fat mass and obesity associated gene (FTO) and pleomorphic adenoma gene 1 (PLAG1) genes associated with obesity was significantly related to the concentration of leptin." (PMID 35498804, 2022). "Among the obesity-related genetic variants, those located in the fat mass and obesity associated (FTO) gene locus, were the first ones that showed a strong association with BMI." (PMID 36452324, 2022). "FTO gene is associated with obesity, and it has been identified as a risk for the development of T2DM in Indians, Europeans, Africans, Western Pacific and American regions." (PMID 37192883, 2022). "Its risk alleles within the 47 kb linkage disequilibrium (LD) block on the FTO sections of intron one and exon two are associated with obesity, wherein energy homeostasis and eating behavior are controlled." (PMID 36530622, 2022). "In mice with fused-toe (Ft) mutation, there is a gene named fat mass and obesity associated (FTO) gene, which is the orthologs gene of human, causing obesity." (PMID 35651949, 2022). "In fact, the two types of m6A demethylases identified so far are FTO (fat mass and obesity-associated gene) and ALKBH5 (alkB homolog 5)." (PMID 35053496, 2022). "The fat mass obesity gene FTO common sequence variant was recently related to the prevalence of a high fat and high carbohydrate diet." (PMID 35565757, 2022). "The fat mass and obesity-associated (FTO) gene was the first gene to show the strongest association with polygenic obesity." (PMID 35409166, 2022). "The FTO gene has been shown to be strongly associated with obesity against the increase in the food intake and BMI." (PMID 36126070, 2022). "The mechanism is associated with inhibiting adipocyte precursor mitochondria thermogenesis via the obesity-related FTO allele in a tissue-autonomous way." (PMID 36224334, 2022).